FLG2 (filaggrin 2)
Diseases named in the same sentence as FLG2 in open-access papers (continued):
Sharing a sentence is not in itself a finding about the gene and the disease.
cancer (6 papers, 2015 to 2023). A tumor composed of atypical neoplastic, often pleomorphic cells that invade other tissues. "Although frequent mutations in the FLG/FLG2 genes have been previously observed in other cancers, the mutations were usually considered random (passenger)." (PMID 34900699, 2021). "Similarly, FLG2 (filaggrin 2) has not been implicated in cancer, but is involved with skin homeostasis through interactions with keratin." (PMID 32734521, 2020). "The potential contribution of taxifolin to HRNR, FLG2, CRCT1, KPRP and other tumor suppressor gene expressions in BC via its impact on cell metabolism is indeed intriguing, considering that metabolic alterations are a typical feature of cancer cells." (PMID 37370814, 2023).
FLG2 also shares sentences with these, for which no sentence is quoted: acral peeling skin syndrome (2 papers); ichthyosis vulgaris (2); acne (1); alopecia areata (1); Alzheimer disease (1); autism spectrum disorder (1); autosomal recessive congenital ichthyosis (1); B-cell non-Hodgkin lymphoma (1); cardiomyopathies (1); cardiovascular diseases (1); cholesteatoma (1); chronic gastritis (1); cystic fibrosis (1); dyskeratosis congenita (1); ectodermal dysplasia (1); Erythema (1); hair diseases (1); inflammatory skin disease (1); keratolytic winter erythema (1); medulloblastoma (1); metastatic cancer (1); pachyonychia congenita (1); Palmoplantar keratoderma (1); peeling skin syndrome 1 (1); peeling skin syndrome 4 (1); psoriasis vulgaris (1); scleroderma (1); sensitization (1); SeSAME syndrome (1); skin disorder (1).
A further 1 disease shares a sentence with FLG2 in 1 paper.